EGFR (epidermal growth factor receptor)
Diseases named in the same sentence as EGFR in open-access papers (continued):
Sharing a sentence is not in itself a finding about the gene and the disease.
non-small cell lung carcinoma (continued). "This study demonstrates that successfully isolated EVs from plasma and bronchoalveolar lavage fluid (BALF) of non-small cell lung cancer (NSCLC) patients contain DNA that can be used for EGFR genotyping through liquid biopsy." (PMID 29374476, 2018). "We tested the potential of piperazine-chitosans in siRNA silensing of EGFR, a pro-angiogenic factor up-regulated in non-small cell lung cancer (NSCLC), one of the most malignant forms of lung cancer." (PMID 29493294, 2018). "Use of epidermal growth factor receptor (EGFR) inhibitors represented by gefitinib and erlotinib has become the standard of treatment for non-small-cell lung cancers (NSCLCs) with activating EGFR mutations." (PMID 30220973, 2018). "These drugs (e.g., the EGFR inhibitor erlotinib) promote significant tumor regressions in appropriate patient populations (e.g., EGFR mutant non-small cell lung carcinoma patients)." (PMID 29874589, 2018). "For this study, we chose the A549 and H1650 [EGFR exon 19 deletion (d746-750)], two cell lines representative of non-small cell lung carcinoma for which gefitinib is indicated." (PMID 30416678, 2018). "This review aims to outline the current state of information on lncRNAs and progress on its role in EGFR-TKIs resistance in non-small cell lung cancer." (PMID 29526180, 2018). "Prospective studies in epidermal growth factor receptor (EGFR) mutant non-small-cell lung cancers (NSCLC) patients with brain metastases (BM)." (PMID 30018881, 2018). "Acquired resistance to EGFR-TKIs such as gefitinib and erlotinib is a critical obstacle in the treatment of EGFR mutant-positive non-small cell lung cancer (NSCLC)." (PMID 30619741, 2018). "Brain metastases (BM) are common in non-small cell lung cancer patients including in molecularly selected populations, such as EGFR-mutant and ALK-rearranged tumors." (PMID 29696132, 2018). "In EGFR-mutant non-small cell lung cancer cell models, for instance, the sequential activation of PI3K/AKT and MAPK signalling co-operatively produced highly proliferative cells that survived exposure to EGFR inhibition." (PMID 30237495, 2018). "The acquisition of resistance to EGFR tyrosine kinase inhibitors (EGFR-TKIs) is one of the major problems in the pharmacotherapy against non-small cell lung cancers; however, molecular mechanisms remain to be fully elucidated." (PMID 30680067, 2018). "It should also be noted that many epidermal growth factor receptor tyrosine kinase inhibitors (EGFR-TKIs; e.g. gefitinib, erlotinib), which are key molecules in non-small cell lung cancer treatment, are substrates of P-gp." (PMID 29979729, 2018). "Epidermal growth factor receptor (EGFR) is the main oncogenic driver in non-small cell lung cancer (NSCLC)." (PMID 30680067, 2018). "EGFR inhibitors have shown promise in the treatment of cancer, particularly in non-small cell lung cancer, however, resistance is observed in the majority of patients." (PMID 30054711, 2018). "Gefitinib is an orally active epidermal growth factor receptor (EGFR) antagonist licensed to treat non-small cell lung cancer." (PMID 30458863, 2018). "In non-small cell lung cancer, FDG-PET uptake and CT-ground-glass-opacity features were associated with treatment-informing traits including EGFR-mutations and ALK-rearrangements." (PMID 29732009, 2018). "In the present study, we carefully examined the EGF-induced degradation of endogenous EGFR proteins in a panel of non-small cell lung cancer cell lines." (PMID 29976202, 2018). "In particular, the exon 19-deletion mutation of EGFR is recurrently observed in non-small cell lung cancer (NSCLC) patients, which accounts for nearly 50% of all EGFR abnormalities." (PMID 29976202, 2018). "EDV nanocells coated with epidermal growth factor receptor (EGFR)-specific antibodies entered a phase I trial for the delivery of miR-16 mimics in patients with malignant pleural mesothelioma or non-small cell lung cancer (NSCLC)." (PMID 29570632, 2018).
non-small cell lung carcinoma (continued). "Non-small cell lung cancer (NSCLC) is characterized by hyperexpression and/or gain-of-function mutations of the epidermal growth factor receptor (EGFR), resulting in an elevated overall kinase activity." (PMID 30237564, 2018). "We have recently reported that PGE2 induces EGFR internalization and nuclear translocation supporting tumor progression in non-small cell lung cancer (NSCLC) cells." (PMID 29599917, 2018). "Epidermal growth factor receptor tyrosine kinase inhibitor (EGFR-TKI) resistance is a major obstacle in the treatment of non-small cell lung cancer (NSCLC)." (PMID 29374157, 2018). "The TKI, gefitinib, a FDA-approved compound for the treatment of non-small-cell lung carcinoma, has recently been tested in human TB due to its ability to inhibit the epidermal growth factor receptor (EGFR) and activate autophagy to restrict bacterial growth." (PMID 30298121, 2018). "Loss of H3K4me3 and increase of H3K9me3 has recently been described in drug induced slow cycling EGFR mutant non-small-cell lung carcinoma and other cancer types." (PMID 29192388, 2018). "Erlotinib is an epidermal growth factor receptor (EGFR)-targeting tyrosine kinase inhibitor approved for treatment of non-small cell lung cancer." (PMID 30116910, 2018). "It was found that epidermal growth factor receptor (EGFR) directly phosphorylates IKKε (Y153, Y159) to promote the oncogenic phenotype of non-small cell lung cancer cells." (PMID 30223576, 2018). "Of particular interest is the fact that MET gene amplification and overexpression leads to resistance to anti-EGFR therapies in non-small cell lung cancer and in brain tumors through receptor co-activation with EGFR." (PMID 30227653, 2018). "Lymphocyte-to-monocyte ratio (LMR) has been previously reported to be a poor prognostic factor in EGFR mutant non-small cell lung cancer and was also included as a covariate." (PMID 30192878, 2018). "Epidermal growth factor receptor (EGFR) tyrosine kinase inhibitors (gefitinib, erlotinib and afatinib) are indicated as first-line therapy in patients with non-small cell lung cancer (NSCLC) whose tumors harbor activating mutations in the EGFR gene." (PMID 29689091, 2018). "The epidermal growth factor receptor tyrosine kinase inhibitors (EGFR-TKIs) and programmed death receptor 1 (PD-1)/programmed death ligand 1 (PD-L1) immune checkpoint inhibitors were landmarks in the treatment of non-small cell lung cancer (NSCLC)." (PMID 30454551, 2018). "Low dose erlotinib-cisplatin combination exhibits its anti-tumor activity by targeting angiogenesis through modulation of c-MYC/HIF-1α/VEGF pathway in non-small cell lung cancer cells with EGFR exon 19 deletions." (PMID 30619741, 2018). "Epidermal growth factor receptor tyrosine kinase inhibitors (EGFR TKIs) are widely applied to treat EGFR-mutant non-small cell lung cancer (NSCLC)." (PMID 29312548, 2017). "Intracranial effect of tyrosine kinase inhibitors ALK inhibitors and epidermal growth factor receptor (EGFR) inhibitors in trials in non-small cell lung cancer (NSCLC)." (PMID 28424757, 2017). "Here, we report our experience using next generation sequencing (NGS) to examine AKT1, BRAF, EGFR, ERBB2, KRAS, NRAS, and PIK3CA genes in 1006 non-small cell lung cancers in a clinical diagnostic setting." (PMID 29228562, 2017). "Second- and third-generation inhibitors of epidermal growth factor receptor (EGFR) tyrosine kinase activity (EGFR-TKIs) are improving the treatment of patients with non-small cell lung cancer." (PMID 29050315, 2017). "Regarding the concordance between the number of EGFR gene copies and primary tumor and metastatic lesions in non-small cell lung cancer, the discordant rate ranges from 27 to 32%." (PMID 28854970, 2017). "Targeting EGFR is an important treatment modality for many solid tumors including non-small cell lung cancer (NSCLC)." (PMID 28467975, 2017).
non-small cell lung carcinoma (continued). "Our findings reveal a new post-transcriptional mechanism of CD73 regulation via miR-30a-5p and EGFR-related drug resistance in non-small cell lung cancer." (PMID 28158983, 2017). "In contrast, the intrinsic induction of PD-L1 on the surface of tumor cells is mediated by constitutive oncogenic and transcriptional pathways, such as the PI3K and mTOR pathways in non-small cell lung cancer and the EGFR-MAP kinase pathway in breast cancer." (PMID 28938605, 2017). "Compared with traditional platinum-based combination chemotherapy, EGFR TKI unprecedentedly brought a better clinical benefit and quickly laid its own position in treating advanced non-small cell lung cancer patients with EGFR mutation." (PMID 29088904, 2017). "EGFR inhibition has been used as a strategy for treatment of non-small-cell lung cancer, pancreatic cancer, breast cancer, colon cancer and some other cancers." (PMID 28703807, 2017). "Incorporation of molecular analysis of the epidermal growth factor receptor (EGFR) gene into routine clinical practice represents a milestone for personalized therapy of the non-small-cell lung cancer (NSCLC)." (PMID 28744312, 2017). "Specifically the molecular testing was performed for the EGFR and KRAS mutational analysis based on the previous or contemporary diagnoses of Non Small Cell Lung Cancer (NSCLC) and colon carcinomas." (PMID 28099523, 2017). "Here we consider polypharmacological targeting of protein kinases ALK, MET, and EGFR (and its drug resistant mutant T790M) in non small cell lung cancer as an example." (PMID 29086093, 2017). "EGFR sensitive mutations, especially in-frame deletions in exon 19 and a point mutation in exon 21 (L858R), are present in 30–40% of non-small cell lung cancer (NSCLC) patients and respond well to EGFR-TKIs such as gefitinib and erlotinib." (PMID 28915624, 2017). "Epidermal growth factor receptor (EGFR) is an oncogene that is involved in the development and progression of several human cancers, including non-small cell lung cancer (NSCLC)." (PMID 28219421, 2017). "A phase II study of preoperative gefitinib in clinical stage I non-small-cell lung cancer demonstrated that tumor shrinkage was frequently seen in women, neversmokers and the EGFR expression (proven by biopsy) was a strong predictor of response." (PMID 28881771, 2017). "Here, we used functional genomics to identify oncogenic miRNAs in non-small cell lung cancer and evaluate their impact on response to epidermal growth factor (EGFR)-targeting therapy." (PMID 27477696, 2017). "The epidermal growth factor receptor (EGFR) is a receptor tyrosine kinase that is commonly upregulated in cancers such as in non-small-cell lung cancer, metastatic colorectal cancer, glioblastoma, head and neck cancer, pancreatic cancer, and breast cancer." (PMID 28513565, 2017). "EGFR-targeted therapy increases the radiosensitivity of non-small cell lung cancer through the inhibition of autophagy." (PMID 29232380, 2017). "Erlotinib is a tyrosine kinase inhibitor that targets the EGFR in locally advanced or metastatic non-small cell lung cancer (NSCLC) that has failed a prior chemotherapy regimen." (PMID 28640223, 2017). "Question 34: Why is epidermal growth factor receptor (EGFR) 19 Del-positive tumor more sensitive to targeted therapy than EGFR 21 L858R-positive tumor in patients with non-small cell lung cancer?" (PMID 28571582, 2017). "Patients with non-small cell lung cancer (NSCLC) usually possess specific mutations in the tyrosine kinase domain of the EGFR gene, the clinical target of EGFR tyrosine kinase inhibitor (EGFR-TKI) therapy." (PMID 28915593, 2017). "In research done on non-small-cell lung cancer the expression of miR-133b also influenced EGFR signalling pathway." (PMID 28377929, 2017). "Molecular analysis of the mutation status for EGFR and KRAS are now routine in the management of non-small cell lung cancer." (PMID 28139704, 2017).
non-small cell lung carcinoma (continued). "Combined treatment with an EGFR tyrosine kinase inhibitor and Akt inhibitor causes apoptosis and synergistic growth inhibition in multiple EGFR tyrosine kinase inhibitor-resistant non-small-cell lung cancer models." (PMID 28871105, 2017). "We previously reported that miR-200s were silenced through promoter methylation in acquired EGFR-tyrosine kinase inhibitor (TKI) resistant non-small cell lung cancer (NSCLC) cells harboring EMT features." (PMID 28084458, 2017). "IGF-IR is involved in epidermal growth factor receptor (EGFR) TK inhibitor (TKI) resistance through crosstalk between IGF-IR and EMT signaling pathways in non-small cell lung cancer (NSCLC) with EGFR mutations." (PMID 28137302, 2017). "GSE4342 is a study that demonstrated the sensitive response of 17 non-small cell lung cancer (NSCLC) cell lines to gefitinib (EGFR-inhibitor) treatment." (PMID 28198666, 2017). "c-MET is considered a promising oncogenic driver in non-small cell lung cancer (NSCLC) after the discovery of epidermal growth factor receptor (EGFR) and anaplastic lymphoma kinase (ALK)." (PMID 28442019, 2017). "EGFR-TKI therapy achieves favorable clinical outcomes for patients with non-small cell lung cancer (NSCLC)." (PMID 28915593, 2017). "Non-small cell lung cancer (NSCLC) patients, with sensitive epidermal growth factor receptor (EGFR) mutations react well to tyrosine kinase inhibitors (TKIs)." (PMID 28855040, 2017). "Although EGFR-TKIs (epidermal growth factor receptor tyrosine kinase inhibitors) induce favorable responses as first-line non-small cell lung cancer treatments, drug resistance remains a serious problem." (PMID 28915593, 2017). "A retrospective study in non-small cell lung cancer investigated the time of development of disease flare after stopping EGFR TKI (either erlotinib or gefitinib) in patients that acquired clinical resistance." (PMID 27853997, 2017). "Epidermal Growth Factor Receptor (EGFR) molecular analysis is performed to assess the responsiveness to Tyrosine Kinase Inhibitors (TKIs) in patients with Non-Small Cell Lung Cancer (NSCLC)." (PMID 28520821, 2017). "Nowadays, 1st generation EGFR-TKIs still are standard treatments for advanced non-small-cell lung cancer (NSCLC) patients." (PMID 29212192, 2017). "In contrast, a non-small cell lung cancer xenograft expressing a constitutively active EGFR conformational mutant exhibited macrophage proximity-independent EGFR activity." (PMID 28166195, 2017). "For instance, Edmonds and co-workers showed that human ovarian carcinoma (OVCAR-5) and non-small cell lung cancer (H460) cell lines upregulated EGFR after PDT with verteporfin (log P = 3.74)." (PMID 27803950, 2017). "EGFR-mutant non-small cell lung cancer are often resistant to EGFR tyrosine kinase inhibitor treatment." (PMID 28871105, 2017). "The EGFR expression level was a predictive marker of survival benefits in advanced non-small-cell lung cancer patients treated with cetuximab and first-line chemotherapy." (PMID 29228748, 2017). "Tyrosine kinase inhibitors, such as erlotinib and gefitinib, are currently frontline therapeutics in EGFR mutant non-small cell lung cancer patients." (PMID 28938622, 2017). "One of the more commonly targeted oncogenic RTKs in Non-Small Cell Lung Cancers (NSCLC) is the Epidermal Growth Factor Receptor (EGFR)." (PMID 28646226, 2017). "We investigated the frequency of concurrent genes in EGFR-mutant non-small cell lung cancer patients and determined its value in predicting the efficacy of EGFR-TKIs treatment." (PMID 28212572, 2017). "EGFR mutations were found in 30% to 60% of Asian patients and 10% to 20% of Caucasian patients with NSCLC (non-small cell lung cancer), while ALK-fusions were found in 2% to 5% of patients." (PMID 29285248, 2017). "A 60-year-old woman who was initially diagnosed with oligometastatic non-small cell lung cancer (NSCLC) (EGFR and ALK-negative) in 2010." (PMID 29207685, 2017).
non-small cell lung carcinoma (continued). "It is known that TGF-β is a growth factor for gastrointestinal tract and pancreatic cancer, similar to EGFR in non-small cell lung cancer." (PMID 28067794, 2017). "A prominent example is the emergence of EGFR T790M “gatekeeper” mutations in tumors at the time of disease recurrence and following initial response to EGFR tyrosine kinase inhibitors in non-small cell lung cancer (NSCLC) patients." (PMID 29299135, 2017). "The clinical knowledge of Epidermal Growth Factor Receptor (EGFR) molecular status and its therapeutic application, emerging in the early 2000s, has revolutionized non-small cell lung cancer (NSCLC) management, paving the way for targeted therapies." (PMID 28427238, 2017). "Among them, we selected the A549 non-small cell lung cancer fibroblast for further analyses because the cell showed the highest expression of the EGFR among the panel of the cancer cell lines." (PMID 28887524, 2017). "Epidermal growth factor receptor-tyrosine kinase inhibitor (EGFR-TKI) has intracranial activity in EGFR-mutant Non-Small Cell Lung Cancer (NSCLC)." (PMID 29340055, 2017). "In the past decade, several molecular-targeted agents, such as epidermal growth factor receptor tyrosine kinase inhibitors (EGFR-TKIs), have emerged and are currently used in the treatment of advanced non-small cell lung cancer (NSCLC)." (PMID 29169381, 2017). "This study aimed to examine the association of clinical prognostic factors with epidermal growth factor receptor-tyrosine kinase inhibitor (EGFR-TKI) efficacy in advanced non-small-cell lung cancer (NSCLC) patients." (PMID 27926500, 2017). "Treatment and clinical-outcomes were described in a sub-cohort of non-small-cell lung cancer (NSCLC) patients with disease-progression (PD) after epidermal growth factor tyrosine kinase inhibitors (EGFR-TKIs) treatment." (PMID 28777825, 2017). "Epidermal growth factor receptor (EGFR) mutant non-small cell lung cancers acquire resistance to EGFR tyrosine kinase inhibitors through multiple mechanisms including c-Met receptor pathway activation." (PMID 27786612, 2017). "Therapies targeting epidermal growth factor receptor (EGFR) can effectively treat with non-small cell lung cancer (NSCLC), but NSCLC’s drug resistance makes it intractable." (PMID 29108234, 2017). "Inhibition of AKT1 enhanced migration and invasion in KRAS- or EGFR-mutant non-small cell lung cancer (NSCLC) cells." (PMID 28765579, 2017). "The selective response of non-small cell lung cancer (NSCLC) patients to EGFR tyrosine kinase inhibitors (TKIs) gefitinib and erlotinib allowed for the identification of oncogenic EGFR mutations." (PMID 29371993, 2017). "Many patients with brain metastases from non-small cell lung cancer have limited survival, while others survive for several years, depending on patterns of spread, EGFR and ALK alterations, among others." (PMID 28651600, 2017). "EGFR is one of the critical oncogenes for several cancers, such as non-small cell lung cancer (NSCLC) and urinary bladder cancer (BC)." (PMID 29156842, 2017). "AZD9291, a third-generation epidermal growth factor receptor (EGFR) tyrosine kinase inhibitor (TKI), benefits patients with T790M mutant non-small-cell lung cancer who fail treatment with first-generation EGFR TKIs." (PMID 28061471, 2017). "Epidermal growth factor receptor (EGFR) tyrosine kinase inhibitors (TKIs) have become standard therapy for advanced non-small cell lung cancer (NSCLC)." (PMID 29340050, 2017). "The discovery of EGFR mutations and EML4-ALK gene rearrangements has radically changed the therapeutic scenario for patients with advanced non-small cell lung cancer." (PMID 28938691, 2017). "Epidermal growth factor receptor (EGFR) T790M mutation has shown to be associated with the clinical outcomes of patients after initial EGFR-tyrosine kinase inhibitor (EGFR-TKI) therapy in EGFR-mutant advanced non-small cell lung cancer (NSCLC)." (PMID 27999211, 2017).